NEIL1 (nei like DNA glycosylase 1)
Diseases named in the same sentence as NEIL1 in open-access papers (continued):
Sharing a sentence is not in itself a finding about the gene and the disease.
hepatocellular carcinoma (2 papers, 2018 to 2025). A malignant tumor that arises from hepatocytes. "Based on RT-qPCR analysis of Orox A-treated hepatocellular carcinoma cells, significant increases in the mRNA transcript levels of NEIL1, OGG1, ATR, and ATM were observed." (PMID 41009509, 2025). "Interestingly, there is evidence that TRIM26 may act as a tumor suppressor in hepatocellular carcinoma, although whether this is directly related to its role in regulation of NEIL1 and NTH1 is unclear." (PMID 29610152, 2018).
ovarian carcinoma (2 papers, 2022 to 2023). A malignant neoplasm originating from the surface ovarian epithelium. "Perhaps due to low expression of NEIL1 in ovarian cancer, we did not observe a higher DDR in ovarian cancer with ADAR1 overexpression." (PMID 35711824, 2022).
polyposis (2 papers, 2022 to 2024). "Blood and normal colonic mucosae even from reference individuals revealed considerable methylation, and examination of blood DNAs from our polyposis cases (with or without NEIL1 variants) raised no suspicion of constitutional NEIL1 epimutation in any case." (PMID 36387175, 2022).
prostate carcinoma (2 papers, 2015 to 2023). A carcinoma that arises from epithelial cells of the prostate gland. "We show herein that NEIL1 protein levels are reduced in response to RAD9 depletion, and that RAD9-mediated NEIL1 protein level regulation is transcriptional in human prostate cancer cells but post-transcriptional in mES cells." (PMID 25873625, 2015). "In summary, we demonstrate that RAD9 can regulate NEIL1 at the transcriptional level in human prostate cancer cells, while in mouse ES cells Rad9 impacts on Neil1 protein levels by controlling proteasomal degradation." (PMID 25873625, 2015). "Our results indicate that NEIL1 protein levels are regulated differently in human prostate cancer cells versus mouse ES cells." (PMID 25873625, 2015). "The prognostic value of HFM1 and NEIL1 were previously reported in rectal and prostate cancers, but their effect on immune cell infiltration remains unclear." (PMID 36708047, 2023). "We observed reduced NEIL1 RNA levels in human prostate cancer cells after RAD9 depletion, and thus wanted to address whether a similar regulatory mechanism was responsible." (PMID 25873625, 2015). "Furthermore, we tested NEIL1 abundance in human prostate cancer DU145 and PC-3 cells with inherent or shRNA-reduced RAD9 levels." (PMID 25873625, 2015). "Thus, we demonstrate that RAD9 regulates BER by controlling NEIL1 protein levels, albeit by different mechanisms in human prostate cancer versus mouse ES cells." (PMID 25873625, 2015). "In human prostate cancer cell lines, DU145 and PC-3, RAD9 does this by activating NEIL1 transcription." (PMID 25873625, 2015). "Also, human prostate cancer cells, DU145 and PC-3, knocked down for RAD9 demonstrate reduced NEIL1 abundance relative to controls." (PMID 25873625, 2015).
radiation pneumonitis (2 papers, 2021 to 2025). Inflammation of the lung due to harmful effects of ionizing or non-ionizing radiation. "NEIL1 mutations were related to the risk of radiation pneumonitis by regulation of NEIL1 expression and acted as independent biomarkers for predicting radiation pneumonitis in patients treated with thoracic radiotherapy." (PMID 40761744, 2025). "Thus, we hypothesize NEIL1 is an important BER gene acts in radiation pneumonitis." (PMID 34105905, 2021).
triple-negative breast carcinoma (2 papers, 2023 to 2025). An invasive breast carcinoma which is negative for expression of estrogen receptor (ER), progesterone receptor (PR), and human epidermal growth factor receptor 2 (HER2). "In the present study, another gene of the DNA glycosylase family involved in the BER pathway has been flagged as being induced by PAC, only in triple-negative breast cancer; it is named NEIL1." (PMID 37298600, 2023).
bladder cancer (1 paper, 2024). "The top 50 differentially expressed genes of germinal center-related B-cell subtypes were put into the TCGA database for comparison, and the expression of LMO2, AICDA and NEIL1 in bladder cancer was observed." (PMID 38216927, 2024).
Cockayne’s syndrome-B (1 paper, 2015). "Loss of NEIL1, Cockayne’s syndrome-B (CSB) and XPA in mice reduces expansion, bolstering the idea that removal of oxidative DNA damage causes instability." (PMID 26247199, 2015).
cognitive decline (1 paper, 2019). "NEIL1 knockout mice studies have demonstrated that NEIL1 plays a crucial role in the prevention of short- and long-memory loss and cognitive decline." (PMID 31415677, 2019).
colon cancer (1 paper, 2020). "One the other hand, high expression of NEIL1 promoted the cell viability and reduced the apoptosis, inducing the balance of Bax/Bcl-2 in the human colon cancer cells to be antiapoptotic." (PMID 32685496, 2020).
colorectal tumor (1 paper, 2022). "Somatic hypermutability and MMR deficiency-associated signatures in a colorectal tumor from an Argentine case with the NEIL1 c.506G>A variant provided critical clues to discover a large genomic deletion of PMS2 as a concomitant germline alteration in this patient." (PMID 36387175, 2022). "Moreover, in FAP104, all five members who were verified to have either one of the NEIL1 variants (or both) had a colorectal tumor phenotype." (PMID 36387175, 2022).
esophageal cancer (1 paper, 2021). A primary or metastatic malignant neoplasm involving the esophagus. "Our previous study found that compared with the NEIL1 rs4462560 GG, rs4462560 GC/CC variant significantly reduced the occurrence of grade ≥2 acute radiation injury after radiotherapy for esophageal cancer." (PMID 34105905, 2021). "Our previous study found NEIL1 rs4462560 G>C may serve as a predictor of RP in esophageal cancer patients who received definitive radiotherapy with or without chemotherapy." (PMID 34105905, 2021). "Our previous study found genetic variations in DNA repair gene NEIL1 may be a predictor of RP in patients with esophageal cancer." (PMID 34105905, 2021).
Fanconi anemia (1 paper, 2013). Fanconi anemia (FA) is a hereditary DNA repair disorder characterized by progressive pancytopenia with bone marrow failure, variable congenital malformations and predisposition to develop hematological or solid tumors. "In addition, loss of NEIL1 function has also been shown to be synthetically lethal with the disruption of the Fanconi anemia DNA repair pathway, in which the disease is characterized by a deficiency in repair and tolerance of interstrand DNA cross-links." (PMID 24349107, 2013).
Huntington disease (1 paper, 2020). Huntington disease (HD) is a rare neurodegenerative disorder of the central nervous system characterized by unwanted choreatic movements, behavioral and psychiatric disturbances and dementia. "In Huntington disease (HD), Ogg1 (and/or Neil1)-initiated repair of 8-oxoguanine (8-oxoG, or oxidized pyrimidines) in CAG triplets is proposed to trigger iterative oxidation–excision cycles that contribute to the somatic instability of the huntingtin gene, through a CAG repeat expansion." (PMID 32192183, 2020).
neuroblastoma (1 paper, 2021). Neuroblastoma (NB) is the most common solid, extracranial childhood tumor. "Protective effects by chelating agents against Cu-mediated inhibition of NEIL1 could be also confirmed in human neuroblastoma SH-SY5Y cells." (PMID 33607499, 2021). "In undifferentiated human neuroblastoma SH-SY5Y cells, Fe (100 μM FeSO4) lowered 5-hydroxyuracil excision from a bubble substrate (NEIL1/2 activity) and AP lyase activity by 50–60%." (PMID 33607499, 2021).
osteosarcoma (1 paper, 2021). A usually aggressive malignant bone-forming mesenchymal neoplasm, predominantly affecting adolescents and young adults. "Laser microirradiation experiments were performed in U2OS (osteosarcoma) cells stably expressing NEIL1-GFP following exposure to TH5487." (PMID 33925271, 2021).
prion disease (1 paper, 2016). A transmissible disease that is caused by a protein that is able to induce abnormal folding of normal cellular proteins, leading to characteristic spongiform brain changes, which are associated with neuronal loss without an inflammatory response. "There was a significant decrease in expression at either onset or end-stage or both for some of the DNA glycosylases (Neil1, Neil2 and Ogg1) in wild-type mice, demonstrating a lack of compensatory up-regulation of brain DNA glycosylases in prion disease." (PMID 27886261, 2016). "Despite the fact that DNA repair capacities appears to be gradually overwhelmed during prion disease, neither this nor the lack of Neil3 elicit any compensatory increase in expression levels of other DNA glycosylases with overlapping substrate specificities (i.e. Neil1 and Neil2)." (PMID 27886261, 2016).
cancer (34 papers, 2012 to 2025). A tumor composed of atypical neoplastic, often pleomorphic cells that invade other tissues. "All three individuals with the NEIL1 c.506G>A variant had colorectal disease (cancer or polyps) and the same applied to the two individuals with the c.821delT variant." (PMID 36387175, 2022). "Single-knockout mice deficient for Neil1 and Nthl1 are phenotypically inconspicuous, the combined knockout, however, is highly cancer prone, indicative of mutual compensation of both factors for oxidative DNA damage repair." (PMID 31566562, 2019). "Our results are consistent with the idea that individuals who harbor the G83D NEIL1 variant are at increased risk for cancer." (PMID 29156764, 2017). "We suggest that individuals who harbor the G83D NEIL1 variant face an increased risk for human cancer." (PMID 29156764, 2017). "The overall goal of this study was to determine if the NEIL1 G83D germline variant has a functional phenotype that is related to cancer." (PMID 29156764, 2017). "Then, the median mutation loads for each cancer type and the median NEIL1, NEIL2, and NEIL3 expression values normalized to the expression value of the constitutive housekeeping gene YWHAZ (ENSG00000164924) were analyzed to identify correlations." (PMID 27042257, 2016). "Future genome-wide analyses of cancers derived from individuals with germline NEIL1 or NEIL2 mutations should clarify the role of NEIL1 and NEIL2 in the prevention of mutations." (PMID 27042257, 2016). "As a mechanism underlying the reduced expression of NEIL1 in cancer, the epigenetic silencing of NEIL1 through promoter hypermethylation was found." (PMID 27042257, 2016). "Numerous studies have indicated that any alteration in NEIL1 expression can lead to the deregulation of cell death and carcinogenesis and reported that, in diverse cancers, the abnormal expressions of NEIL2 were widely associated with the somatic mutation load." (PMID 37298600, 2023). "We identified one Pan-Cancer – TCGA OC carrier of a synonymous variant in NEIL1 c.159C>T; p.Gly53Gly that was predicted to affect splicing using SpliceAI that may result in gain of a new donor splice site." (PMID 36969007, 2023). "The decreased level or loss of activity of NEIL2 and, to a lesser extent, NEIL1, is a risk factor for the progression of cancers such as lung cancer and squamous cell carcinoma in the oral cavity, and poor survival in patients with estrogen-receptor-positive breast cancer." (PMID 32872214, 2020). "As the major regulator of BER, NEIL1 is associated with the development of many types of cancers." (PMID 32685496, 2020). "Ectopic expression of a rare human NEIL1 germline variant devoid of glycosylase activity induced replication stress, DNA breaks and anchorage-independent growth, suggesting that it confers an increased risk for cancer." (PMID 32547565, 2020). "These phenotypes are often associated with carcinogenesis and suggest that individuals who harbor the NEIL1 G83D variant may be at increased risk for cancer." (PMID 29156764, 2017). "Our results are consistent with the suggestion that individuals who harbor the germline SNP encoding for NEIL1 G83D have increased levels of genomic instability that could predispose them to the development of cancer." (PMID 29156764, 2017). "Using data for 13 cancer types from the TCGA database, we revealed that the median somatic total and SNP-type mutation loads exhibited significant inverse correlations with the median NEIL1 and NEIL2 expression levels and a significant positive correlation with the median NEIL3 expression level." (PMID 27042257, 2016). "NEIL1, a BER-initiating glycosylase, has been associated with mutation burden in human cancers when underexpressed." (PMID 41275076, 2025). "In conclusion, our findings provide new insights into the role of interactions between RPA and NEIL1 in multiple DNA repair pathways and suggest previously unrecognized targets for therapeutic inhibition of DNA repair in cancers." (PMID 39025455, 2024).
cancer (continued). "In family F1506, the index carrier harbouring ERCC5 c.2556 A>G also had a remarkable family history of diverse cancer types, whereas the index carrier of NEIL1 c.248G>T; c.1268-1G>T from family F1601 had a cancer family history consistent with HBOC syndrome." (PMID 36969007, 2023). "As NEIL1 is commonly hypermethylated in cancer, we designed a MS-MLPA kit to determine constitutional and somatic methylation status of our patient samples." (PMID 36387175, 2022). "Data analysis from TCGA database suggested that nine cancer types exhibit epigenetic silencing of the NEIL1 gene through promoter hypermethylation." (PMID 34105905, 2021). "It was reported that the expression of NEIL1 and NEIL2 inversely correlated with the number of somatic mutations in several cancers, whereas NEIL3 showed a positive correlation." (PMID 32547565, 2020). "The reduced expression of NEIL1, NEIL2, and elevated expression of NEIL3 is involved in the progression of several types of cancer as a consequence of somatic mutation load." (PMID 32872214, 2020). "We found, for the first time, that the abnormal expressions of NEIL1, NEIL2, and NEIL3 are associated with somatic mutation loads in diverse cancers." (PMID 27042257, 2016). "Using a TCGA-based analysis, associations between abnormal NEIL1, NEIL2, or NEIL3 expressions and the somatic mutation load were apparently demonstrated in various cancer types for the first time." (PMID 27042257, 2016). "In this study, we found 9 cancer types that showed epigenetic silencing of the NEIL1 gene via promoter hypermethylation using data from the TCGA database." (PMID 27042257, 2016). "We also showed that a subset of human cancers exhibited reduced NEIL1 and NEIL2 expression levels and an elevated NEIL3 expression level, and these abnormal expressions of NEIL1, NEIL2, and NEIL3 were associated with the mutation load in cancer." (PMID 27042257, 2016). "Together with a previous finding that the region around the transcription start site of the NEIL1 gene exhibits promoter activity, these results suggest that these cancer types exhibit epigenetic silencing of the NEIL1 via promoter hypermethylation." (PMID 27042257, 2016). "We genotyped this variant in our defined FC cancer study groups and controls, and we did not identify any other carriers of this NEIL1 variant or in any of the additional 553 FC OC cases." (PMID 36969007, 2023). "The relationship between NEIL1 and cancers pathogenesis have been investigated." (PMID 34105905, 2021). "Recently, we reported no accumulation of DNA damage or mutations and no predisposition to cancer development in mice lacking both NEIL1 and NEIL234." (PMID 34857879, 2021). "However, the development of NEIL1 inhibitors is still in its infancy and we await results using appropriate cancer cell and animal models." (PMID 32648895, 2020). "Furthermore, siRNA knockdown of NEIL1 (and also PARP1) was synthetic lethal with FANCG loss (involved in DNA interstrand cross-link repair), sporadic mutations of which occur in several cancers." (PMID 32648895, 2020). "Neil1,2,3 triple-mutant mice were recently reported to be viable, but mice were only analyzed- and reported negative for cancer predisposition." (PMID 31566562, 2019). "We next investigated whether the abnormal expressions of NEIL1, NEIL2, and NEIL3 were associated with the mutation load in each cancer type." (PMID 27042257, 2016). "Next, we attempted to investigate the expression statuses of NEIL1, NEIL2, and NEIL3 in each cancer type and to determine whether their abnormal expressions were associated with the mutation load of each cancer." (PMID 27042257, 2016). "Finally, we investigated the impact of the reduction in NEIL1 expression in cancer on the overall survival of the patients." (PMID 27042257, 2016).